BCL7A (BAF chromatin remodeling complex subunit BCL7A)
Diseases named in the same sentence as BCL7A in open-access papers (continued):
Sharing a sentence is not in itself a finding about the gene and the disease.
depression (1 paper, 2024). "To investigate the correlation between cancer and depression, we examined the expression of BCL7A, GPR18, GRB10, KLRG1, TDRD9, and THEM4 across various cancer types using the TCGA database." (PMID 39867577, 2024). "qPCR results demonstrated that, compared to the normal control group, the expression of GRB10 and TDRD9 was significantly elevated in the blood of depression patients, while the expression of BCL7A, GPR18, KLRG1, and THEM4 was significantly reduced." (PMID 39867577, 2024). "This study conducted a comprehensive bioinformatics analysis, identifying six core genes (BCL7A, GPR18, GRB10, KLRG1, TDRD9, and THEM4) associated with depression and validating their diagnostic value in the context of the disorder." (PMID 39867577, 2024). "We identified six core genes (GRB10, TDRD9, BCL7A, GPR18, KLRG1, and THEM4) significantly associated with depression and cancer." (PMID 39867577, 2024). "The results indicated that BCL7A (AUC: 0.656), GPR18 (AUC: 0.9677), GRB10 (AUC: 0.678), KLRG1 (AUC: 0.661), TDRD9 (AUC: 0.698), and THEM4 (AUC: 0.678) exhibit high diagnostic value for depression." (PMID 39867577, 2024). "In depression, GRB10 and TDRD9, involved in cell growth and stress responses, exhibited elevated expression, while BCL7A, GPR18, KLRG1, and THEM4, linked to immune regulation and apoptosis, showed reduced expression, suggesting dysregulated cellular signaling and impaired immune function." (PMID 39867577, 2024). "The results showed that the expression levels of GRB10 and TDRD9 were significantly increased in depression patients compared to the control group, while the expression levels of BCL7A, GPR18, KLRG1, and THEM4 were significantly decreased, all with statistical significance." (PMID 39867577, 2024). "We identified six core genes (BCL7A, GPR18, GRB10, KLRG1, TDRD9, and THEM4), confirming their critical value in diagnosing depression." (PMID 39867577, 2024). "Among them, GRB10 and TDRD9 were significantly upregulated, while BCL7A, GPR18, KLRG1, and THEM4 were significantly downregulated in patients with depression." (PMID 39867577, 2024). "These pathways suggest that BCL7A, GPR18, KLRG1, and THEM4 play roles in immune signaling and metabolic pathways, further underscoring their relevance to depression." (PMID 39867577, 2024). "To more accurately predict and assess the progression of depression, we constructed a nomogram model for depression diagnosis based on the core genes (GRB10, TDRD9, BCL7A, GPR18, KLRG1, and THEM4) using the rms package." (PMID 39867577, 2024). "Similarly, BCL7A, GPR18, KLRG1, and THEM4, which are downregulated in depression, also exhibit diverse expression trends across cancers." (PMID 39867577, 2024).
melanoma (1 paper, 2020). A malignant, usually aggressive tumor composed of atypical, neoplastic melanocytes. "Polymorphisms in genes involved in DNA repair (POLN, PRKDC), immune regulation (IL9), and apoptosis (BCL7A, BCL2L1) have also been associated with increased melanoma risk, and in some instances, these polymorphisms (IL9 and BCL7A) have stronger risks in CDKN2A-positive families." (PMID 33076392, 2020).
memory impairment (1 paper, 2017). "Taken together, these findings suggest that neuron-specific Bcl7a deficiency does not lead to memory impairments, while it affects the dendritic branching of Purkinje cells and leads to motor dysfunction." (PMID 29213114, 2017).
myeloma (1 paper, 2025). "Our mutation profile (ARID1A, KMT2D, BCL7A, PTPN11, NUP214) and high CNV load converge with patterns reported across extramedullary/myeloma cohorts, notably MAPK pathway lesions and 1q amplifications." (PMID 41378284, 2025).
non-Hodgkin lymphoma (1 paper, 2021). Distinct from Hodgkin lymphoma both morphologically and biologically, non-Hodgkin lymphoma (NHL) is characterized by the absence of Reed-Sternberg cells, can occur at any age, and usually presents as a localized or generalized lymphadenopathy associated with fever and weight loss. "BCL7A, a member of the BCL7 family, was identified as a risk factor associated with Burkitt lymphoma, non-Hodgkin’s lymphoma, and cutaneous T cell lymphoma." (PMID 34362400, 2021).
plasma cell neoplasm (1 paper, 2025). A clonal proliferation of immunoglobulin-secreting plasma cells. "These somatic alterations have been implicated in various processes central to plasma cell neoplasms, from chromatin remodeling (ARID1A, KMT2D, and BCL7A) to oncogenic signaling (PTPN11, NUP214)." (PMID 41378284, 2025).
primary immunodeficiency (1 paper, 2024). "The high BCL7A subgroup was enriched in pathways related to DNA replication, mismatch repair, primary immunodeficiency, and the low BCL7A subgroup was enriched in pathways such as Rig-I-like receptor signaling and the renin-angiotensin system." (PMID 39867577, 2024).
prostatic cancer (1 paper, 2019). "Hypermethylation of RASGRF2 has been associated with recurrence of prostatic cancer; BCL7B is a member of the BCL7 gene family (along with the genes BCL7A and BCL7C), in humans, the decrease in BCL7A expression is associated with development of NHL and epithelial lymphoma." (PMID 30908498, 2019).
retinoblastoma (1 paper, 2017). A malignant tumor that originates in the nuclear layer of the retina. "They experimentally demonstrated that let-7b was down-regulated in retinoblastoma and the target mRNAs of let-7b, such as CDC25A and BCL7A, were over-expressed." (PMID 28793339, 2017).
thyroid cancer (1 paper, 2022). "Finally, germline variants in BCL7A had opposite effects in thyroid cancer when stratifying tumors by purity." (PMID 35725412, 2022).
thyroid tumor (1 paper, 2022). A benign or malignant neoplasm affecting the thyroid gland. "In low-purity thyroid tumors, the variant ieQTL allele was associated with slightly lower BCL7A expression, but the same allele was associated with higher BCL7A expression in high-purity thyroid tumors." (PMID 35725412, 2022).
cancer (17 papers, 2007 to 2025). A tumor composed of atypical neoplastic, often pleomorphic cells that invade other tissues. "Among the SNV top-ranked promoters (DMD), DHS elements (LRMP) and enhancers (PAX5, BACH2, BCL2, CXCR4, and BCL7A) are highly cancer-type-specific cases with many BCL or CLL mutations." (PMID 29354286, 2018). "All these genes have already been associated with hypermutated regions in BCLs (BCL2, BCL6, BCL7A, BIRC3, CIITA and ST6GAL1) or listed in the Cancer Gene Census (BCL2, BCL6, BCL7A, BIRC3, CIITA, IGLL5 – in the IGL@ locus – and LPP)." (PMID 25903198, 2015). "For example, overexpression of GRB10 and TDRD9 may enhance cancer cell proliferation, while downregulation of BCL7A, GPR18, KLRG1, and THEM4 could contribute to reduced immune surveillance and tumor evasion." (PMID 39867577, 2024). "Based on our observations that AKR1C3 and BCL7A have known functions in cancer and that ieQTLs in these genes are likely to be specific to tumor cells, we looked for other ieGenes across the datasets that may also play a role in cancer biology." (PMID 35725412, 2022). "Among 38 probes, 27 were annotated in GO: 6 were for the major lymphoid-restricted membrane protein (JAW1), 2 for the B-cell CLL/lymphoma 7A (BCL7A), 2 for phosphoinositide-3-kinase, catalytic, gamma polypeptide (PIK3CG) and 2 for cancer susceptibility candidate 1 (CASC1)." (PMID 17888167, 2007). "Thus, our work pinpointing the role of these evolutionarily conserved subunits frequently perturbed in human cancer may suggest exciting therapeutic opportunities for chemically fine-tuning SWI/SNF remodeling activities through targeting BCL7A/B/C proteins." (PMID 38296999, 2024). "miRNA targeted gene pathway interaction identified BCL7A, BCL2L1, LIN28A, KLF6, GATA6, solute carrier family genes and ZNF genes associated with erythropoiesis, cell cycle regulation, glycosphingolipid biosynthesis, cAMP, cGMP-PKG, mTOR, MAPK and PI3K-AKT signaling pathways and cancer pathways." (PMID 36295630, 2022). "Results indicated that core genes can influence cancer progression by regulating immune cells, with BCL7A and GRB10 showing positive correlations with immune cell infiltration in most cancers." (PMID 39867577, 2024). "For instance, BCL7A and GRB10, which were found to be protective factors in certain cancers, are known to regulate immune-related pathways and cellular signaling, potentially enhancing anti-tumor immunity and suppressing oncogenic activity." (PMID 39867577, 2024). "Twelve genes were frequently targeted in both cohorts independently, including BCL2, BCL6, BCL7A, CD74 and CIITA, all listed as oncogenes in the Cancer Gene Census and known to be involved in lymphomagenesis." (PMID 25903198, 2015). "We demonstrate here that the paralogous cancer-related minor SWI/SNF subunits DPF1, -2, -3; BCL7A, -B, -C; and SS18 and SS18L1 reside in BAF-class human SWI/SNF complexes and, that PHF10 marks PBAF SWI/SNF complexes." (PMID 22442726, 2012). "We additionally draw attention to the BAF chromatin remodeler BCL7A, for which we found no ASCL1 connection in the literature, and which is also associated with diverse cancers." (PMID 40257984, 2025). "For instance, BCL7A and GRB10 showed protective roles in some cancers, possibly through mechanisms such as enhancing immune infiltration or suppressing oncogenic pathways, while THEM4, TDRD9, and KLRG1 acted as risk factors in others, potentially by inhibiting tumor suppressor functions." (PMID 39867577, 2024). "Genes such as BCL7A and GRB10 may exert anti-cancer effects by promoting immune cell infiltration, whereas KLRG1, THEM4, and TDRD9 might suppress immune cell infiltration, facilitating tumor progression." (PMID 39867577, 2024).
tumor (17 papers, 2009 to 2026). "Taken together, our results suggest that BCL7A modulates the expression of key genes that can be linked to a tumor suppressor phenotype in the AML context." (PMID 36941700, 2023). "Recently, our group showed that mutations in the first splice donor site of BCL7A cause an in-frame deletion of 27 codons in its first exon, impairing its tumor suppressor function in DLBCL." (PMID 36810086, 2023). "In this study, we report that BCL7A significantly is associated with tumor malignancy." (PMID 34362400, 2021). "In vivo and cellular assays further validate the pivotal role of the arginine anchor in BCL7A-mediated tumor suppression." (PMID 41485079, 2026). "Altogether, our study identifies the BCL7A arginine anchor as a key molecular switch that links nucleosome binding to chromatin remodeling and tumor suppression, making it a potential therapeutic target for DLBCL." (PMID 41485079, 2026). "This subunit is frequently mutated in DLBCL, and reintroduction of wild type BCL7A impaired the proliferation of DLBCL cells both in vitro and in vivo, pointing to a tumor suppressor role." (PMID 36810086, 2023). "The bioluminescence reduction evinced a lower tumorigenic ability in the presence of BCL7A, corroborating its tumor suppressor role in vivo." (PMID 36941700, 2023). "These mutations often affect different alleles from the same sample, suggesting biallelic inactivation patterns that are consistent with a tumor suppressor role of BCL7A in DLBCL." (PMID 36810086, 2023). "GO and GSEA analyses revealed the potential contribution of BCL7A in adaptive immune response and neutrophil activation in the tumor microenvironment." (PMID 34362400, 2021). "Among the few upregulated genes detected with quantitative RT-PCR, BCL7A has been classified as a tumor suppressor gene, while CXCL10 mediates a thymus-dependent antitumor response in vivo." (PMID 19123925, 2009). "Truncation or DLBCL-associated mutations of this anchor impair BCL7A's tumor-suppressive function without affecting its integration into the complexes." (PMID 41485079, 2026). "Therefore, our in vivo experiments confirmed that BCL7A expression restoration promotes a tumor suppressor phenotype in NB4 cells." (PMID 36941700, 2023). "In the present study, we show the first experimental evidence of a tumor suppressor role of BCL7A in vivo and in vitro in AML, finding that some tumors silence BCL7A expression by promoter methylation and presenting the first functional models that support its tumor suppressor role." (PMID 36941700, 2023). "In addition, restoration of BCL7A expression exerts tumor suppressor activity in AML cell lines and xenograft models." (PMID 36941700, 2023). "The possible reason might be that BCL7A-regulated precancerous cells in the tumor microenvironment undergo EMT and then acquire the phenotype of infiltration and chemoresistance." (PMID 34362400, 2021). "Indeed, some anti‐ or pro‐apoptotic genes, as some members of BCL family, as BCL2 and BCL7A, can indirectly be involved with neoplasias due to their capacity to activate caspases." (PMID 32073752, 2020). "As an important tumour suppressor gene, BCL7A actively participates in the growth of tumours." (PMID 31077237, 2019). "Additionally, restoration of BCL7A expression reduced tumor growth in an NB4 mouse xenograft model." (PMID 36941700, 2023). "Furthermore, we evaluated the tumor suppressor activity of BCL7A through in vivo xenograft studies." (PMID 36941700, 2023). "Oncogenes show specific activity in tumor cells, with LMO2, LYN, TNFRSF17, CARD11, and BCL7A being active in Tumor B1, while BCL2 and WAS are specifically active in Tumor B2." (PMID 41238550, 2025). "Also, differential expression analysis found that BCL7A restoration altered cell cycle pathways and modified significantly the expression of genes like HMGCS1, H1-0, and IRF7 which can help to explain its tumor suppressor role in AML." (PMID 36941700, 2023).
tumor (continued). "TIMER was applied to explore the correlation of BCL7A with immune cell infiltration and reported a significant negative-correlation between BCL7A expression in tumor cells and the infiltration of neutrophil cells in LGG and GBM." (PMID 34362400, 2021). "Restoration of BCL7A hindered cell proliferation in competition cell growth assay and xenograft tumor formation in vivo modulating significantly the expression of genes such as HMGCS1, H1-0, and IRF7, which may help to explain its tumor suppressor role in AML." (PMID 36941700, 2023). "Restoration of BCL7A expression in cell culture impaired cell proliferation in competition cell growth assay and tumor formation on xenografts in vivo, altering the expression of genes like HMGCS1, H1-0, IRF7, which may help to explain its tumor suppressor role in AML." (PMID 36941700, 2023).
BCL7A also shares sentences with these, for which no sentence is quoted: acute myeloid leukemia (2 papers); B-cell CLL (1); breast carcinoma (1); glioblastoma (1); hematological malignancies (1); Hodgkins lymphoma (1); lung adenocarcinoma (1); lung carcinoma (1); lymphoid neoplasm (1); medulloblastoma (1); mycosis fungoides (1); myeloid leukemia (1); ovarian serous cystadenocarcinoma (1); peripheral T-cell lymphoma (1); Stroke (1); tuberculosis (1); uveal melanoma (1); Williams-Beuren syndrome (1).